KIF20A (kinesin family member 20A)
Description:
Mitotic kinesin required for chromosome passenger complex (CPC)-mediated cytokinesis. Following phosphorylation by PLK1, involved in recruitment of PLK1 to the central spindle. Interacts with guanosine triphosphate (GTP)-bound forms of RAB6A and RAB6B. May act as a motor required for the retrograde RAB6 regulated transport of Golgi membranes and associated vesicles along microtubules. Has a microtubule plus end-directed motility.
Synonyms: MKlp2; RAB6KIFL; RCM6
Tractability: Small molecule: a high-quality ligand is known. PROTAC: ubiquitination databases record sites on it; a small molecule that binds it is known.
Target class: Other cytosolic protein
Gene: Protein-coding gene on chromosome 5 (138,178,719 to 138,188,171, forward strand). Ensembl gene ENSG00000112984.
Subcellular location: Golgi apparatus; Cytoplasm, cytoskeleton, spindle
Subcellular location (Human Protein Atlas): Cleavage furrow; Cytokinetic bridge; Mitotic spindle; Nucleoplasm
Pathways (Reactome):
Cell Cycle: Mitotic Telophase/Cytokinesis
Hemostasis: Kinesins
Immune System: MHC class II antigen presentation
Vesicle-mediated transport: COPI-dependent Golgi-to-ER retrograde traffic
Gene Ontology:
Molecular function: protein binding; protein kinase binding; ATP binding; microtubule binding; microtubule motor activity
Biological process: microtubule bundle formation; midbody abscission; mitotic cytokinesis; regulation of cytokinesis; microtubule-based movement
Cellular component: midbody; mitotic spindle; spindle; kinesin complex; nucleoplasm; nucleus; Golgi apparatus
Genetic constraint (gnomAD): Loss-of-function variants: 65 observed, 116.71 expected, observed/expected ratio (o/e) 0.56, 90% interval 0.46 to 0.69. The upper end of that interval is the gene's LOEUF score, 0.69, which puts it in group 2 of 6, group 1 being the genes least tolerant of losing a copy. Missense variants: 925 observed, 1,134.9 expected, observed/expected ratio (o/e) 0.82, 90% interval 0.77 to 0.86. Synonymous variants: 376 observed, 427.79 expected, observed/expected ratio (o/e) 0.88, 90% interval 0.81 to 0.96.
Gene-disease validity (ClinGen):
ClinGen rates the evidence that KIF20A causes each of these diseases.
congenital heart disease (autosomal recessive): Limited. A heart disease that is present at birth.
Homologues: Orthologues: chimpanzee KIF20A (99% identical), macaque KIF20A (98% identical), pig KIF20A (94% identical), dog KIF20A (93% identical), rabbit KIF20A (91% identical), guinea pig KIF20A (91% identical), rat Kif20a (87% identical), mouse Kif20a (87% identical), tropical clawed frog kif20a (63% identical), zebrafish kif20a (47% identical). Paralogues in human: KIF23 (24% identical), KIF13B (19% identical), KIF1B (19% identical), CENPE (18% identical), KIF15 (18% identical), KIF21B (18% identical), KIF5A (18% identical), KIF16B (18% identical), KIF5B (18% identical), KIF13A (18% identical), KIF4A (18% identical), KIF1A (18% identical), and 29 more.
Diseases named in the same sentence as KIF20A in open-access papers:
KIF20A is named in the same sentence as 101 diseases in open-access papers, as found by Europe PMC text mining. Sharing a sentence is not in itself a finding about the gene and the disease. The quoted sentences say what the papers report.
breast carcinoma (44 papers, 2013 to 2025). "Validation using UALCAN, GEPIA, and Kaplan-Meier plotters revealed that three key genes-RACGAP1, SPAG5, and KIF20A-were significantly overexpressed and associated with poor prognosis in breast cancer (BC), as well as advanced tumor staging." (PMID 39988630, 2025). "Findings from several studies have indicated that KIF20A is abnormally expressed in tumor tissues and associated with poor prognosis for patients with soft tissue sarcoma, ovarian cancer, and breast cancer." (PMID 34659201, 2021). "Elevated levels of KIF20A have also been correlated with ANCCA (AAA nuclear co-regulator cancer associated) levels in breast cancer tumors, whose overexpression is associated with poor patient outcomes." (PMID 27941992, 2016). "According to our findings, miR-153-3p has a direct effect on KIF20A and may regulate the formation of intracellular vesicles, which in turn makes breast cancer cells more susceptible to doxorubicin." (PMID 36980610, 2023). "KIF20A is reportedly associated with paclitaxel resistance in breast cancer and could therefore be a therapeutic target for refractory breast cancer." (PMID 34593983, 2023). "KIF20A has been shown to arrest breast cancer cell division at G2/M phase, ultimately leading to cell death." (PMID 41392981, 2025). "It has been demonstrated that abnormal expression of KIF20A is observed in various solid tumors, including glioma, hepatocarcinoma, breast cancer, nasopharyngeal cancer, gastric cancer, and lung cancer." (PMID 41462522, 2025). "To confirm that KIF20A regulates breast cancer stemness, we assessed the expression of canonical stem cell markers (Oct4, Sox2, or NANOG) and found that KIF20A siRNA transfection led to decreased mRNA levels of these markers in Hs578T cells." (PMID 41392981, 2025). "KIF20A is highly expressed in almost all cancers, including gastric cancer, melanoma, hepatocellular carcinoma, and breast cancer." (PMID 39371335, 2024). "KIF20A was overexpressed in bladder and breast cancer tissues; after suppressing KIF20A, the growth of cancer cells was inhibited." (PMID 36798768, 2023). "The usage of bioinformatics tolls resulted in the identification of AURKA, AURKB, TTK, MELK and KIF20A as top 5 hub genes involved in breast cancer occurrence and progression." (PMID 37231064, 2023). "In breast cancer, suppressing endogenous KIF20A using small interfering ribonucleic acids or paprotrain, a specific inhibitor of KIF20A, significantly inhibited breast cancer cell growth." (PMID 36798768, 2023). "According to the TCGA database analysis, the expression of KIF20A was relatively higher in the tumor than in normal tissues in breast cancer." (PMID 36980610, 2023). "FOXM1 regulated KIF20A to modulate paclitaxel sensitivity in breast cancer, as well as in docetaxel resistance of prostate cancer." (PMID 36798768, 2023). "Kinesins have been recently highlighted as prognostic biomarkers in breast cancer and a 6-KIFs-based risk score (including four MT-Rel genes, KIF4A, KIF15, KIF18B, KIF20A) was reported to accurately predict outcomes." (PMID 37835564, 2023). "The findings of this study demonstrate that miR-153-3p upregulation is a crucial moderator that increases breast cancer cells’ Dox sensitivity and can directly target and downregulate KIF20A, which is essential for controlling the malignant process." (PMID 36980610, 2023). "Recently, abnormal KIF20A expression has been found in breast cancer, cervical squamous cell carcinoma, and hepatocellular carcinoma, suggesting that this gene is closely related to the formation and development of tumors." (PMID 35149954, 2022). "Recent studies have demonstrated that KIF20A is overexpressed in many malignant tumors, including gastric cancer, glioma, bladder cancer, breast cancer, and prostate cancer." (PMID 36619388, 2022). "KIF20A (also named RAB6KIFL), has been reported overexpressed in many cancers including pancreatic cancer, melanoma, breast cancer, and glioma 33-37." (PMID 33403046, 2021).
breast carcinoma (continued). "KIF20A has been reported to be implicated in FOXM1-related chemoresistance in hepatocellular carcinoma and breast cancer." (PMID 33292277, 2020). "KIF20A was found to be involved in paclitaxel resistance and has the potential to be a predictive biomarker for breast cancer treatment." (PMID 33173433, 2020). "Kif20a is abnormally highly expressed in various tumors, such as gastric cancer 7, glioma, pancreatic cancer, breast cancer and bladder cancer." (PMID 32742456, 2020). "Lysosomal stability was demonstrated to enhance the survival of breast cancer cells while the knocking down of KIF20A conduced the permeabilization of the lysosomal membrane, which in turn, causing cellular death." (PMID 32322170, 2020). "Studies have found that KIF20A is highly expressed in many types of tumours, such as lung cancer, breast cancer, gastric cancer, liver cancer, bladder cancer, and pancreatic cancer." (PMID 31093305, 2019). "Accordingly, paclitaxel has been shown to target the expression of FOXM1 and its downstream target the kinesin KIF20A, to drive abnormal mitotic spindle formation, mitotic catastrophe and senescence in breast cancer cells." (PMID 29540677, 2018). "Khongkow and colleagues reported that paclitaxel targets FoxM1 to regulate KIF20A in mitotic catastrophe and dysfunction of FoxM1 expression will lead to breast cancer paclitaxel resistance." (PMID 29416660, 2018). "Based on previous studies, KIF20A has been overexpressed in lung and breast cancer, otherwise low levels are inspected in the placenta and heart." (PMID 30369945, 2018). "KIF20A is overexpressed in various tumor types, including pancreatic cancer, bladder cancer, gastric cancer, melanoma, hepatocellular carcinoma and breast cancer." (PMID 28081138, 2017). "Together these results suggest that FOXM1 regulates KIF20A to modulate paclitaxel sensitivity in breast cancer." (PMID 25961928, 2016). "Similar to FOXM1, KIF20A expression is downregulated by paclitaxel in the sensitive MCF-7 breast cancer cells and deregulated in the paclitaxel-resistant MCF-7TaxR cells." (PMID 25961928, 2016). "The physiological relevance of the regulation of KIF20A by FOXM1 is further highlighted by the strong and significant correlations between FOXM1 and KIF20A expression in breast cancer patient samples." (PMID 25961928, 2016). "In agreement, depletion of FOXM1 by siRNA downregulates KIF20A expression and paclitaxel downregulates FOXM1 and therefore, KIF20A expression in MCF-7 breast cancer cell lines." (PMID 25961928, 2016). "With regards to its role in tumorigenesis, KIF20A has been shown to be essential for chromosome segregation and mitosis in breast cancer, and KIF20A expression correlates with poor disease-free survival (DFS) in patients with ER-positive breast cancer." (PMID 27941992, 2016). "The significance of both FOXM1 and KIF20A in survival analyses provides further evidence for the involvement of both genes in breast cancer progression and drug response." (PMID 25961928, 2016). "In breast cancer, KIF20A expression was shown to modulate mitotic spindle formation and mitotic catastrophe, which is important in paclitaxel-mediated cell death and senescence." (PMID 27941992, 2016). "KIF20A expression is elevated in various cancers, including breast cancer." (PMID 41392981, 2025). "Similarly to our findings, suppression of endogenous KIF20A inhibited the growth of cells in breast cancer." (PMID 41392981, 2025). "Furthermore, KIF20A overexpression correlates with poor prognosis and serves as an independent prognosis factor in breast cancer patients." (PMID 41392981, 2025). "Notably, a study has shown that KIF20A expression is downregulated in paclitaxel-sensitive breast cancer cells but elevated in paclitaxel-resistant ones." (PMID 41392981, 2025).
breast carcinoma (continued). "Masako Nakamura’s research elucidates KIF20A’s pronounced expression in different breast cancer subtypes compared to normal tissue, identifying it as an independent marker of prognosis and a potential target for therapy, with its suppression resulting in a halted cell cycle and cancer cell death." (PMID 39272816, 2024). "Furthermore, an analysis of breast cancer subtypes revealed that KIF20A was expressed in 195 (75.9%) tumor samples, while it was rarely detected in normal breast tissues." (PMID 39272816, 2024). "In this study, we found miR-153-3p could target KIF20A to sensitize breast cancer cells to doxorubicin." (PMID 36980610, 2023). "In breast cancer, KIF20A predicted a poor prognosis and was an independent prognostic factor, as well as in bladder cancer, cervical squamous cell carcinoma, epithelial ovarian cancer, gastric cancer, glioma, medulloblastoma, melanoma, nasopharyngeal carcinoma, and ovarian clear-cell carcinoma." (PMID 36798768, 2023). "Taken together, we demonstrated that miR-153-3p treatment enhanced the chemosensitivity of breast cancer cells to doxorubicin by downregulating KIF20A, leading to disrupted intracellular vesicle formation and doxorubicin-triggered cancer cell death by activating various pathways." (PMID 36980610, 2023). "KIF20A is also involved in taxane resistance in breast cancer cells." (PMID 36980610, 2023). "Moreover, overexpression of KIF20A was correlated with various human cancers, such as gastric cancer, lung cancer, and breast cancer, implying a cancer-related function." (PMID 35204562, 2022). "Upregulation of KIF20A has been demonstrated in numerous types of cancer, and is an independent prognostic factor for poor clinical outcomes for early-stage cervical squamous cell carcinoma, glioma and breast cancer." (PMID 32963620, 2020). "The high expression of KIF20A leads to paclitaxel resistance in breast cancer cell lines." (PMID 31093305, 2019). "In addition, these data also underscore the value of FOXM1 and KIF20A as biomarkers for the prediction of breast cancer chemotherapy sensitivity and patient survival." (PMID 25961928, 2016). "Furthermore, knockdown of KIF20A strongly impeded proliferation and induced apoptosis of both tamoxifen-sensitive and tamoxifen-resistant breast cancer cells." (PMID 27941992, 2016). "Also, AURKB and KIF20A, the other two genes amongst five critical genes which are introduced as pivotal targets for prospective drug discovery and inhibitor designing, were indicated to play a crucial role in breast carcinoma metastasis to the skin." (PMID 37231064, 2023). "In addition to pathological functions and therapeutic value, KIF20A has been recognized as an independent prognostic factor for various malignant cancers, such as bladder cancer, colorectal cancer, breast cancer, gastric cancer, epithelial ovarian cancer, and NSCLC." (PMID 36619388, 2022). "However, KIF20A overexpression conferred resistance to paclitaxel in breast cancer cases." (PMID 36096734, 2022). "Interestingly, our gene promoter and ChIP analyses reveal that this FHRE is located downstream of the most 5'-transcription start site, within the first non-coding exon, suggesting FOXM1 drives the transcription of KIF20A from this alternative promoter region in breast cancer cells." (PMID 25961928, 2016). "While these studies link KIF20A to cell cycle and cell division control, our study explores its connection to metabolism, specifically OXPHOS, in breast cancer." (PMID 41392981, 2025). "Besides, several bioinformatics studies have shown that KIF20A is a type of glycolytic gene and has an important predictive value for the diagnosis as well as the prognosis of tumors, such as hepatocellular carcinoma, retinoblastoma, cervical cancer, and breast cancer." (PMID 36927438, 2023).
breast carcinoma (continued). "FOXM1, a forkhead family of transcription factor, is involved in the regulation of cell proliferation and mitosis by regulating transcription of p27kip1, cyclin D1, cdc25, KIF20A, and CENP-A in breast cancer." (PMID 37025658, 2023). "GEPIA analysis disclosed that breast cancer patients have significantly higher expression of AURKA (4.0 vs. 1.5), AURKB (4 vs. 1), TTK (2.5 vs. 0.5), MELK (3.0 vs. 0.5), KIF20A (3.5 vs. 0.5) genes compared to healthy people." (PMID 37231064, 2023). "In line with our studies, other groups reported that ASPM, KIF20A, TPX2, AURKA and KIF2C are among the top 11 up-regulated hub key genes identified as potential breast cancer prognostic biomarkers." (PMID 37835564, 2023). "Ectopic expression of KIF20A promoted chemoresistance of CRC cells to oxaliplatin or 5-FU treatment by decreasing apoptosis 37 and also indicated that expression of KIF4A, KIF15, KIF20A and KIF23 was correlated with prognosis in breast cancer." (PMID 33995648, 2021). "Elevated expression levels of kinesins KIF14, KIF4A, KIF20A, and KIF23, KIF2C, and KIFC1 have been reported in breast cancer cell lines, other kinesins KIF10, KIF18A, and KIF15 have been linked to prognostic indicators in breast cancer patients." (PMID 32346924, 2020). "In this study we evaluate the potential MGMT’s role in control of therapeutic, clinically relevant, cell cycle regulators involved in breast cancer oncogenesis (CDC2, TOP2A, AURKB, CDC20, KIF20A, Cyclin A2, Cyclin B2, Cyclin D1)." (PMID 30038716, 2018). "We show that O6-benzylguanine (BG), an MGMT inhibitor decreases CDC2, CDC20, TOP2A, AURKB, KIF20A, cyclin B2, A2, D1, ERα and survivin and induces c-PARP and p21 and sensitizes ER positive breast cancer to temozolomide (TMZ)." (PMID 30038716, 2018). "We found that KIF23, KIF20A, KIF4A, KIFC1 and PRC1 were expressed at high levels in all investigated breast cancer cell lines." (PMID 28061449, 2017). "Our immunohistochemical and statistical analysis of breast cancer patient samples shows that there is a significant and strong correlation between FOXM1 and KIF20A expression, further confirming the regulation of KIF20A by FOXM1 in vivo." (PMID 25961928, 2016). "We next tested the effects of targeting FOXM1 and KIF20A in MCF-7 and the paclitaxel-resistant MCF-7 TaxR breast cancer cell lines." (PMID 25961928, 2016). "Although miR-153 has multiple targets in different cancers, its relationship with doxorubicin resistance and KIF20A has not previously been clarified in breast cancer cells." (PMID 36980610, 2023). "FOXM1 plays a role in regulating radiosensitivity in glioma and breast cancer cells, and FOXM1 may enhance radiation resistance in part by inducing KIF20A expression." (PMID 35574421, 2022). "Additionally, study found that 26 of 38 kinesins detected in breast cancer MCF-7 cells are regulated by estrogen 17β-estradiol (E2) and many of them are upregulated by E2, including KIF15, KIF4A, KIF20A, and KIF23." (PMID 31729978, 2019). "In addition, BG+/-TMZ significantly decreased p-CDC2, p-AURKB, p-TOP2A, p-KIF20A and p-CDC20 expression in breast cancer cells." (PMID 30038716, 2018). "This study is aimed to evaluate expression and transcription correlations between MGMT and already clinically relevant cell cycle regulators involved in breast cancer oncogenesis, chemotherapy resistance (TOP2A for anthracyclines, KIF20A for taxol) and hormonal therapy resistance (ARUKB)." (PMID 30038716, 2018).